SPATA13 (spermatogenesis associated 13)
Description:
Acts as a guanine nucleotide exchange factor (GEF) for RHOA, RAC1 and CDC42 GTPases. Regulates cell migration and adhesion assembly and disassembly through a RAC1, PI3K, RHOA and AKT1-dependent mechanism. Increases both RAC1 and CDC42 activity, but decreases the amount of active RHOA. Required for MMP9 up-regulation via the JNK signaling pathway in colorectal tumor cells. Involved in tumor angiogenesis and may play a role in intestinal adenoma formation and tumor progression.
Synonyms: Asef2; FLJ31208; ARHGEF29
Tractability: Antibody: its Gene Ontology location is reachable by antibodies, with medium confidence. PROTAC: ubiquitination databases record sites on it.
Gene: Protein-coding gene on chromosome 13 (23,979,805 to 24,307,074, forward strand). Ensembl gene ENSG00000182957.
Subcellular location: Cytoplasm; Cell projection, filopodium; Cell projection, lamellipodium; Cell projection, ruffle membrane; Cell projection, podosome
Subcellular location (Human Protein Atlas): Nucleoplasm; Cytosol
Pathways (Reactome):
Signal Transduction: CDC42 GTPase cycle; RAC1 GTPase cycle
Gene Ontology:
Molecular function: guanyl-nucleotide exchange factor activity; protein binding
Biological process: cell migration; filopodium assembly; lamellipodium assembly; regulation of cell migration; regulation of small GTPase mediated signal transduction
Cellular component: cytoplasm; cytosol; filopodium; lamellipodium; nucleoplasm; ruffle membrane; podosome
Genetic constraint (gnomAD): Loss-of-function variants: 47 observed, 99.8 expected, observed/expected ratio (o/e) 0.47, 90% interval 0.37 to 0.6. The upper end of that interval is the gene's LOEUF score, 0.6, which puts it in group 2 of 6, group 1 being the genes least tolerant of losing a copy. Missense variants: 1,250 observed, 1,470.3 expected, observed/expected ratio (o/e) 0.85, 90% interval 0.81 to 0.89. Synonymous variants: 493 observed, 567.55 expected, observed/expected ratio (o/e) 0.87, 90% interval 0.81 to 0.94.
Gene-disease validity (ClinGen):
ClinGen rates the evidence that SPATA13 causes each of these diseases.
primary angle-closure glaucoma (autosomal dominant): Limited.
Homologues: Orthologues: chimpanzee SPATA13 (99% identical), macaque SPATA13 (94% identical), rabbit SPATA13 (75% identical), dog SPATA13 (72% identical), rat Spata13 (71% identical), mouse Spata13 (71% identical), tropical clawed frog spata13 (58% identical), zebrafish spata13 (42% identical). Paralogues in human: ARHGEF9 (25% identical), TRIO (13% identical), KALRN (13% identical), MCF2 (12% identical), MCF2L (12% identical), TIAM2 (11% identical), PLEKHG4B (11% identical), TIAM1 (11% identical), MCF2L2 (10% identical), ARHGEF40 (10% identical), PLEKHG4 (10% identical), PLEKHG2 (8% identical), and 10 more.
Diseases named in the same sentence as SPATA13 in open-access papers:
SPATA13 is named in the same sentence as 20 diseases in open-access papers, as found by Europe PMC text mining. Sharing a sentence is not in itself a finding about the gene and the disease. The quoted sentences say what the papers report.
colorectal tumor (3 papers, 2020 to 2024). "Our method introduced SPATA13 a guanine-factor as a novel amplification driver gene in colorectal carcinoma, required for MMP9 up-regulation via the JNK signaling pathway in colorectal tumor cells." (PMID 38195844, 2024).
thyroid cancer (3 papers, 2018 to 2024). "It is noteworthy that the last study showed novel loci containing genes that were previously implicated in thyroid cancer (e.g., HES1, SPATA13, DIRC3, ID4) and a positive association of TSH with VEGFA expression, therefore angiogenesis." (PMID 39767631, 2024). "Importantly, this was the first study to identify SPATA13 as a gene that was associated with both PACG and any eye disease, though GWAS have implicated the gene product (protein SP-1277) with other disorders such as anorexia nervosa, thyroid cancer, and intellectual disability." (PMID 33396423, 2020).
alcohol dependence (2 papers, 2017 to 2019). Physical and psychological dependence on alcohol. "Prior GWAS has shown that variants in SPATA13 are associated with psychological disorders, such as depression and alcohol dependence." (PMID 28820441, 2017).
Intellectual disability (2 papers, 2019 to 2020). "Within the brain Spata13 can modulate glutamatergic dendritic spine formation and evidence from human patients suggests that the gene is associated with intellectual disability." (PMID 31020388, 2019). "A recent study combining microarray and exome sequencing of patients with non-syndromic intellectual disability (ID) identified a missense mutation in SPATA13 in 16 patient families." (PMID 31020388, 2019). "While the potential mechanism by which this mutation may modulate the development of intellectual disability is unknown, it is notable that SPATA13 has been demonstrated to affect dendritic spine formation and that altered spine dynamics have been associated with ID and related symptoms." (PMID 31020388, 2019).
intestinal tumours (2 papers, 2019 to 2021). "Loss of Spata13, also known as the adenomatous polyposis coli exchange factor Asef2, has no identifiable phenotype although it has been shown to reduce the number and size of intestinal tumours in Apc (Min/+) mice." (PMID 31020388, 2019). "SPATA13 is a discrete region in the adult brain enriched in a guanylate exchange factor, and deletion of SPATA13 has been shown to reduce and shrink the number and size of intestinal tumours in Apc (Min/+) mice, but its study in lung cancer is rare." (PMID 34804921, 2021).
lung carcinoma (2 papers, 2021 to 2023). "Compared with normal tissues, the expression of ADM2, CLIC6, KIF20A, LAD1, MUC5B, and TNS4 was up-regulated, and the expression of ATG16L2, KCNK3, MAFF, NKD1, and SPATA13 was down-regulated in lung cancer tissues." (PMID 34804921, 2021).
primary angle-closure glaucoma (2 papers, 2020 to 2023). An angle-closure glaucoma characterized by closure of the anterior chamber angle by an intrinsic defect such that aqueous outflow is blocked and the intraocular pressure becomes inappropriately elevated leading to optic nerve damage and visual field loss. "For SPATA13 gene, it has been reported to be associated with primary angle-closure glaucoma pathogenesis, by regulating nucleotide exchange factors activity and affecting homeostasis in the mitosis in the retina, RPE, cornea and lens etc." (PMID 37696869, 2023).
Anxiety (1 paper, 2019). Intense feelings of nervousness, tension, or panic often arise in response to interpersonal stresses. "Other behavioural aspects such as fear conditioning, anxiety-like behaviour, working memory, and thermal and mechanical sensitivity were not affected by the KO of Spata13 despite the gene’s enriched expression in the central extended amygdala." (PMID 31020388, 2019).
psoriasis (1 paper, 2025). An autoimmune condition characterized by red, well-delineated plaques with silvery scales that are usually on the extensor surfaces and scalp. "A 2019 proteomic study identified SLFN5 among a set of new disease-associated proteins in psoriasis, alongside other markers (ATM, ZNF512, SPATA13, etc.)." (PMID 41328434, 2025).
cancer (3 papers, 2017 to 2024). A tumor composed of atypical neoplastic, often pleomorphic cells that invade other tissues. "However, the association between SPATA13 and tumor size or T stage in cancer has not yet been reported." (PMID 38893126, 2024). "However, the association between SPATA13 mutations and survival has not been reported in any cancer, including RCC." (PMID 38893126, 2024).
tumor (2 papers, 2018 to 2024). "In the Korean-KIRP dataset, SPATA13 mutations were additionally associated with tumor size (p = 0.013) and T stage (p = 0.018)." (PMID 38893126, 2024).
SPATA13 also shares sentences with these, for which no sentence is quoted: depression (2 papers); anorexia nervosa (1); breast tumors (1); colon cancer (1); colorectal carcinoma (1); diabetes (1); hypothyroidism (1); neuropathies (1); Sepsis (1).